ZNF703 (zinc finger protein 703)
Diseases named in the same sentence as ZNF703 in open-access papers (continued):
Sharing a sentence is not in itself a finding about the gene and the disease.
breast carcinoma (continued). "HER2-zero breast cancer was found to have gains in 08q24.21 (MYC) and 08p11.23 (FGFR1, ADGRA2, ZNF703)." (PMID 37264417, 2023). "It has been reported that ZNF703 induces EMT by inhibiting E-cadherin expression, thereby enhancing breast cancer cell invasion and resistance to sorafenib." (PMID 35164660, 2022). "Understanding the process of amplicon formation, an example of which we present here for the chr8:ZNF703/FGFR1 and chr11:CCND1 co-amplifications, will be important for our understanding of the origins of a subset of breast cancers." (PMID 30252041, 2018). "The chr8:ZNF703/FGFR1 and chr11:CCND1 amplifications are amongst the most frequent in breast cancer, particularly in ER-positive breast tumours (19% and 28%, respectively, of amplifications in ER-positive tumours; 11% and 16%, respectively, of total cohort)." (PMID 30252041, 2018). "Co-amplifications of other driver loci in breast cancer are observed, for example chr20:ZNF217 and chr8:MYC is seen in 18 samples (P = 1e−04) and chr20:ZNF217 and chr8:ZNF703 in 11 samples (P = 9e−03) (available at Annals of Oncology online)." (PMID 30252041, 2018). "In this study, we found that ZNF703 is a downstream target gene of SPRY4-IT1 and demonstrated that ZNF703 promotes ER(−) breast carcinoma cell proliferation and suppresses apoptosis in vivo." (PMID 25742952, 2015). "ZNF703 knockdown in MDA-MB-134 and HCC1500 luminal B-type breast cancer cell lines by siRNA significantly decreased survival rates when cells were treated with tamoxifen." (PMID 23991038, 2013). "The MCF-7 luminal A-type breast cancer cell line had low ZNF703 expression levels, while MDA-MB-134 and HCC1500, luminal B-type breast cancer cell lines, had high expression levels, similar to observations in previous studies." (PMID 23991038, 2013). "The other three loci (ZNF703, INHBB, and AREG) have strong links to breast cancer, estrogen regulation, and breast development." (PMID 22747683, 2012). "Cell-type-specific TWAS using MiXcan identified five genes (ADGRV1, ZNF703, TMEM245, CDYL2, and PSG4), including three novel breast cancer susceptibility genes, that were not identified by either PrediXcan or PredictDB." (PMID 36690614, 2023). "Six of these genes (MRPS30, SETD9, ADGRV1, ZNF703, PRR33, and PSG4) showed different directions of association with breast cancer in epithelial vs. stromal (nonepithelial) cells." (PMID 36690614, 2023). "Although miR-491-5p was also found to target JMJD2B and ZNF-703 to act as a tumor suppressor in breast cancer no investigations to pinpoint that RABIF is a direct target of miR-491-5p in breast cancer especially in TNBC in the past." (PMID 34685504, 2021). "In breast cancer the genes at the most telomeric part of the amplicon, ERLIN2 and ZNF703, display the higher frequency of amplification (11.8% and 11.7% of breast cancer cases, respectively), while the frequency of amplification decreases in more centromeric genes of 8p11.23 locus." (PMID 32987805, 2020). "Other chromosome arms with significant differences in the frequencies of putative copy number alterations between the ZNF703-amplified and non-amplified cohorts in the breast cancer TCGA study include 17q and 1q (x2p = 0.006 and 0.004, respectively)." (PMID 32987805, 2020). "The distribution of Aneuploidy Scores (ASs) was not significantly different in cancers with ZNF703 amplifications compared with ZNF703 non-amplified breast cancers." (PMID 32987805, 2020). "Copy number aberrations (CNAs) in known breast cancer driver genes present in the PDTXs included gains/amplifications of MYC (78%), CCNE1 (34%), ZNF703 (25%), CCND1 (31%), MDM2 (25%), and ERBB2 (9%) and deletions of PTEN (41%), PPP2R2A (72%), CDKN2A (47%), and CDKN2B (47%)." (PMID 27641504, 2016). "Recently, Reynisdottir found that high ZNF703 expression, independent of amplification, is correlated with poorer prognosis for breast cancer patients with ER-positive luminal tumors, particularly of the luminal B subtype." (PMID 25742952, 2015).
breast carcinoma (continued). "High ZNF703 expression, independent of the amplification, correlated with worse prognosis for the breast cancer patients with ER-positive luminal tumors, particularly of the luminal B subtype." (PMID 24156016, 2013). "The phenomenon that ZNF703 repressed ERα expression is not contradictory with our results showing that ZNF703 was highly expressed in luminal breast cancer." (PMID 23991038, 2013). "Thus, the down regulation of ZNF703 and SNAI1 by HOXA11 overexpression may contribute to breast cancer suppression." (PMID 28038461, 2017).
breast tumors (12 papers, 2012 to 2023). "Of the final two associations, one lies in the 8p12 region amplified in breast tumors (near ZNF703) and the last lies near AREG, which plays a role mediating estrogen function in breast development." (PMID 22747683, 2012). "Furthermore, ZNF703 seemed to be associated with PR loss, exhibiting more ZNF703 amplification events in ER+PR-HER2- breast tumors than ER+PR+HER2- breast tumors." (PMID 35236318, 2022). "ZNF703 (zinc finger protein 703) is an oncogene that is commonly amplified in luminal B breast tumors, and has been shown to regulate genes involved in proliferation, invasion, and an altered balance of progenitor stem cells." (PMID 36690614, 2023). "Our data suggest that ZNF703 expressed in 34.2% of triple-negative human breast tumors by immunohistochemistry." (PMID 35236318, 2022). "Target DEGs of miR-30c in our analysis were mostly related to the anti-apoptosis of abnormal tumor cells, including MAP3K9 in lung cancer, ST6GALNAC5 in prostate cancer, CSRNP3 in clear renal cell carcinoma, ZNF703 in breast tumors, and CLSPN in brain tumors." (PMID 36700234, 2022). "GATA3, ZNF703, and MAP3K1 are in the group 1 genes associated with acquired endocrine therapy resistance in breast tumors expressing ESR1 and ERBB2." (PMID 29738475, 2018). "Our mapping of the 8p12-p11 region in 359 Nordic breast tumors resulted in the identification of ZNF703 as the only full-length gene within the minimal region of amplification." (PMID 24156016, 2013). "Our mapping of 8p12-p11 and analyses of ZNF703 mRNA and protein expression in breast tumors support ZNF703 as an oncogene in luminal B tumors." (PMID 24156016, 2013). "ZNF703, CTCF, and GNAS alterations were exclusively observed among HR‐positive/HER2‐negative patients, which was consistent with what was observed in a study on 11 616 breast tumors." (PMID 35971249, 2022). "Recent research showed that ZNF703 is amplified in approximately 15% of breast tumors, which is only less than HER2 and cyclin D1 (CCND1), especially in Luminal B molecular subtypes; thus, more attention has been focused on ZNF703." (PMID 26063961, 2015). "A positive correlation between amplification and mRNA expression of ZNF703 in breast tumors has not been observed consistently." (PMID 24156016, 2013).
colorectal cancer (7 papers, 2015 to 2023). A primary or metastatic malignant neoplasm that affects the colon or rectum. "ZNF703 overexpression is associated with poor prognosis in luminal BC, colorectal cancers, head and neck squamous carcinomas, cholangiocarcinomas, and ovarian cancers." (PMID 37514116, 2023). "Two studies from China also discovered that ZNF703 acts as an oncogene that accelerates malignant progression in gastric cancer and is associated with worse prognosis in colorectal cancer patients." (PMID 26063961, 2015). "In colon cancer, ZNF703 inhibition can hinder the proliferation and migration of colorectal cancer cells, which is considered as a potential therapeutic target for metastatic colon cancer." (PMID 34552622, 2021). "Consistent with previous data in which ZNF703 was overexpressed not only in breast but gastric and colorectal cancer and high ZNF703 expression contributed to tumor aggressiveness, our investigations reached much similar conclusions in cholangiocarcinoma." (PMID 27764785, 2016). "Other studies using siRNA showed that knockdown of ZNF703 expression inhibited papillary thyroid carcinoma, medullary thyroid carcinoma, and colorectal cancer cell proliferation and migration comforting ZNF703 as an oncogene and a potential therapeutic target for other advanced cancers." (PMID 37514116, 2023).
gastric cancer (6 papers, 2015 to 2023). A primary or metastatic malignant neoplasm involving the stomach. "ZNF703 overexpression was also reported in other cancers such as gastric cancers, non-small cell lung, PTC, MTC, and HCC." (PMID 37514116, 2023). "For instance, TYMSOS through binding the miR-4739 and resulting in the elevated expression of ZNF703 gives rise to the progression of gastric cancer." (PMID 35211508, 2021). "For instance, LBX2-AS1 is up-regulated in gastric cancer and silencing LBX2-AS1 restrains proliferative, migratory, and invasive capacities of gastric cancer cells by miR-491-5p/ZNF703, miR-219a-2-3p/FUS or miR-4766-5p/CXCL5 axis." (PMID 34552959, 2021).
cholangiocarcinoma (3 papers, 2016 to 2023). A carcinoma that arises from the intrahepatic biliary tree (intrahepatic cholangiocarcinoma) or from the junction, or adjacent to the junction, of the right and left hepatic ducts (hilar cholangiocarcinoma). "Based on the results, we proposed a hypothesis that ZNF703 is positive associated with invasion and metastasis in cholangiocarcinoma cells." (PMID 27764785, 2016). "In the present study, we investigated the role of ZNF703 in cholangiocarcinoma, especially into the effect on tumor proliferation, migration and invasion." (PMID 27764785, 2016). "This study aimed to investigate the expression of ZNF703 in cholangiocarcinoma (CCA) and attempted to elucidate its biological effects in CCA progression." (PMID 27764785, 2016). "Based on these results, we boldly speculate that ZNF703 could be a novel oncogene of cholangiocarcinoma and even promote tumor progression." (PMID 27764785, 2016). "Data from clinical and experimental researches had revealed that ZNF703 could be considered as a candidate oncogene in some digestive malignancies, while nobody had ever explored its role in the development and progression of cholangiocarcinoma as far as we can investigate." (PMID 27764785, 2016). "In the present study, we disclosed that ZNF703 was upregulated in CCA and its overexpression could increase the oncogenic potential especially proliferation, migration and metastasis of cholangiocarcinoma." (PMID 27764785, 2016).
colon cancer (3 papers, 2016 to 2025). "Within the top 20 TFs that showed high correlation between their own CNV and expression, we observed known colon cancer drivers ZNF703 and SMAD4, as well as IRF2 and GATA6, whose DNA aberrations are likely oncogenic." (PMID 41114645, 2025). "Four prognostic hub genes associated with M2 macrophages in colon cancer were identified as follows: ANK4B, CTSD, TIMP1, and ZNF703, and the stability of these results was verified by different clustering methods and GSE39582 dataset." (PMID 34552622, 2021). "In only one of these reports ZNF703 expression has been investigated quantitatively at the mRNA level using qRT‐PCR in a small group of patients with colon cancer." (PMID 27650486, 2016).
head and neck squamous cell carcinoma (3 papers, 2015 to 2023). A squamous cell carcinoma that arises from any of the following anatomic sites: lip and oral cavity, nasal cavity, paranasal sinuses, pharynx, larynx, and salivary glands. "ZNF703 plays an important role in the occurrence and development of head and neck squamous cell carcinoma, non-small cell lung cancer and other tumors." (PMID 34552622, 2021).
lung carcinoma (3 papers, 2016 to 2023). "The aim of our study was to investigate the role of the ZNF703 gene in association with Akt/mTOR activation in non‐small cell lung cancer (NSCLC)." (PMID 27650486, 2016). "In lung cancer, samples with ZNF703 amplification displayed variable mRNA overexpression, suggesting an imperfect correlation." (PMID 36902501, 2023). "Our results indicate that ZNF703 is a new candidate gene in lung cancer and may contribute to the development of lung tumors by activating the Akt/mTOR pathway." (PMID 27650486, 2016).
ovarian carcinoma (3 papers, 2020 to 2023). A malignant neoplasm originating from the surface ovarian epithelium. "The aim of the present study was to investigate the epigenetic regulation of ZNF703 in ovarian cancer, reveal the pathways involved, the underlying mechanism, and determine how this affects ovarian cancer progression and the survival time of patients." (PMID 33246486, 2020). "In conclusion, this is the first study to describe the role and underlying mechanism of ZNF703’s oncogenic action in the development of ovarian cancer." (PMID 33246486, 2020). "To study the role and underlying mechanism of HE4 and ZNF703 interactions in the development of ovarian cancer, we examined their subcellular distribution and localization in cells in which they were overexpressed or inhibited." (PMID 33246486, 2020). "Univariate analysis results showed that high expression of ZNF703, clinical analysis and lymph node metastasis were risk factors affecting the prognosis of ovarian cancer patients." (PMID 33246486, 2020). "Taken together, these results indicate that the ZNF703 expression level was up-regulated in ovarian cancer tissues and was associated with poor prognosis." (PMID 33246486, 2020). "In the future, ZNF703 may be used as a prognostic factor and trigger new research ideas for further understanding the underlying pathogenesis and improving the diagnosis and treatment of ovarian cancer." (PMID 33246486, 2020). "Next, we tested the effects of HE4 in promoting the malignant biological behavior of ovarian cancer by ZNF703." (PMID 33246486, 2020). "This study found that ZNF703 was overexpressed in ovarian cancer, and the survival time of patients with high expression of ZNF703 was significantly shortened." (PMID 33246486, 2020). "A total of 98 samples of ovarian cancer were divided into the ZNF703 high-expression group (++/+++) and the ZNF703 low-expression group (−/+)." (PMID 33246486, 2020). "Immunohistochemistry was used to analyze the expression of ZNF703 in ovarian cancer patients and to assess the effect of ZNF703 expression on the survival and prognosis of ovarian cancer patients." (PMID 33246486, 2020). "ChIP-sequencing technology was used to detect the binding of ZNF703 on chromatin in ovarian cancer cells." (PMID 33246486, 2020). "In this study, the ChIP-seq was used to determine genome-wide target sites of ZNF703 in OVCAR3 ovarian cancer cells." (PMID 33246486, 2020). "ZNF703 overexpression and suppression expression experiments were used to evaluate the effect of ZNF703 on malignant biological behavior of ovarian cancer cells in vitro." (PMID 33246486, 2020). "To evaluate the expression of ZNF703 in ovarian cancer patients, we performed immunohistochemical staining of paraffin sections from clinical specimens." (PMID 33246486, 2020). "ZNF703 was highly expressed in ovarian cancer tissues, and its expression level is related to the prognosis of ovarian cancer patients." (PMID 33246486, 2020). "The results of a previous study, showed the obvious effects of ZNF703 on the proliferation and apoptosis of ovarian cancer." (PMID 33246486, 2020). "Chromatin immunoprecipitation-sequencing (ChIP-Seq), dual luciferase reporter assay, ChIP-PCR, in vivo model were applied to study the molecular mechanism of ZNF703 affecting the development of ovarian cancer." (PMID 33246486, 2020). "At the same time, the opposite trend was observed in ovarian cancer cells in which ZNF703 expression was inhibited." (PMID 33246486, 2020). "In vivo and in vitro experiments confirmed that ZNF703 overexpression/inhibition expression will promoted/inhibited the malignant biological behavior of ovarian cancer." (PMID 33246486, 2020). "Regarding cell invasion and migration, the ability of ovarian cancer cells to invade and migrate decreased after the expression of ZNF703 was inhibited, and increased after ZNF703 overexpression." (PMID 33246486, 2020).
ovarian carcinoma (continued). "The results in ovarian cancer cell lines also confirmed that ZNF703 could activate the PI3K/AKT pathway to promote the malignant biological behaviors of ovarian cancer cells." (PMID 33246486, 2020). "ZNF703 promoted the malignant behavior of ovarian cancer cells through the PI3K-AKT pathway." (PMID 33246486, 2020). "However, when siRNA was used to down-regulate the expression of ZNF703 in the ovarian cancer cell lines, cell proliferation slowed down and apoptosis increased; moreover, cell cycle arrest at the G1 phase was observed." (PMID 33246486, 2020). "Follow-up of 98 patients with ovarian malignant tumors (as of April 30, 2019), and Kaplan-Meier survival analysis showed that the overall survival of ovarian cancer patients with high expression of ZNF703 was shorter than that of patients with low expression of ZNF703 (P = 0.017)." (PMID 33246486, 2020). "However, the role and mechanism of ZNF703 in ovarian cancer are unclear." (PMID 33246486, 2020). "The results showed that ZNF703 as an oncogene played an important role in the epigenetic modification of ovarian cancer proliferation, and suggested that ZNF703 as a transcription factor may become a prognostic factor and a potential therapeutic target for ovarian cancer." (PMID 33246486, 2020). "However, the genomic binding pattern of ZNF703 in ovarian cancer remains unknown." (PMID 33246486, 2020). "We discovered ZNF703 while investigating HE4’s protein-protein interactions using the Y2H assay and performing a gene library screening to identify interactions between HE4 and interacting proteins in the early stage of ovarian cancer (unpublished data)." (PMID 33246486, 2020). "We found that ZNF703 could restore the proliferation, invasion and migration functions inhibited by HE4 in ovarian cancer cells." (PMID 33246486, 2020). "Furthermore, ZNF703 played a significant role in promoting cancer gene expression, but this seemed inconsistent with previous studies in which PEA15 was found to inhibit ovarian cancer cell proliferation." (PMID 33246486, 2020).
triple-negative breast carcinoma (3 papers, 2022 to 2023). An invasive breast carcinoma which is negative for expression of estrogen receptor (ER), progesterone receptor (PR), and human epidermal growth factor receptor 2 (HER2). "Knockdown of ZNF703 in triple-negative breast cancer cells was shown to inhibit the expression of cyclin D1, CDK4, CDK6, and E2F1 and upregulation of Rb1." (PMID 37686244, 2023). "In this most recent study, ZNF703 amplification occurred in 18.2% of triple-negative breast cancer patients, indicating the potential role played in TNBC development." (PMID 35236318, 2022). "Also, ZNF703 can induce G1-phase arrest and is an important protein involved in triple-negative breast cancer progression." (PMID 35928440, 2022). "In the present study, for the first time, we discovered that ZNF703 was also expressed in part of triple-negative breast cancer, whether in the human tumor specimens or cancer cell lines." (PMID 35236318, 2022).
hepatocellular carcinoma (2 papers, 2020 to 2023). A malignant tumor that arises from hepatocytes. "Here we report a new function of Zinc Finger Protein 703 (ZNF703), a member of the NET/NlZ family of zinc finger transcription factors, in promoting hepatocellular carcinoma metastasis." (PMID 32269215, 2020).
colorectal tumor (1 paper, 2016). "In accordance with our results they have found that the ZNF703 gene is overexpressed in 72.7% (16/22) of the colorectal tumor tissues." (PMID 27650486, 2016).